TSPY3 (testis specific protein Y-linked 3)
Description:
May be involved in sperm differentiation and proliferation.
Synonyms: CT78
Tractability: PROTAC: ubiquitination databases record sites on it.
Gene: Protein-coding gene on chromosome Y (9,398,421 to 9,401,223, forward strand). Ensembl gene ENSG00000228927.
Subcellular location: Cytoplasm; Nucleus
Subcellular location (Human Protein Atlas): Cytosol
Gene Ontology:
Biological process: nucleosome assembly
Cellular component: chromatin; cytoplasm; nucleus
Homologues: Orthologues: macaque TSPY2 (71% identical), zebrafish tspy (28% identical), Drosophila melanogaster Set (23% identical), Caenorhabditis elegans spr-2 (19% identical), Drosophila melanogaster Nap1 (15% identical), Caenorhabditis elegans nap-1 (14% identical), Drosophila melanogaster CG3708 (12% identical), Drosophila melanogaster mil (12% identical), zebrafish nap1l4a (12% identical). Paralogues in human: TSPY10 (100% identical), TSPY4 (100% identical), TSPY9 (99% identical), TSPY1 (99% identical), TSPY2 (99% identical), TSPY8 (99% identical), TSPYL1 (34% identical), TSPYL4 (32% identical), TSPYL5 (31% identical), TSPYL2 (31% identical), TSPYL6 (29% identical), SET (26% identical), and 6 more.
Diseases named in the same sentence as TSPY3 in open-access papers:
TSPY3 is named in the same sentence as 3 diseases in open-access papers, as found by Europe PMC text mining. Sharing a sentence is not in itself a finding about the gene and the disease.
TSPY3 shares sentences with these, for which no sentence is quoted: Azoospermia (1 paper); cancer (1); infertile (1).